PGR (progesterone receptor)
Diseases named in the same sentence as PGR in open-access papers (continued):
Sharing a sentence is not in itself a finding about the gene and the disease.
breast cancer (continued). "Since breast cancer cells are divided into different subtypes according to the expression of the estrogen receptor, progesterone receptor, and HER‐2, we selected different types of cells to validate our protein constructs." (PMID 34697906, 2021). "Breast cancer is a heterogeneous disease, divided into subtypes based on the expression of estrogen receptor (ER), progesterone receptor (PR), and human epidermal growth factor receptor 2 (HER2)." (PMID 34464510, 2021). "In fact, in some cases, BCL-2 expression correlates with improved clinical outcome, for example in patients with Estrogen Receptor (ER)- and Progesterone Receptor (PR)-positive breast cancer who received adjuvant endocrine therapy." (PMID 33799592, 2021). "The most useful receptors in breast cancer cells, which determine therapy strategy, are estrogen receptor (ER), progesterone receptor (PR) and human epidermal growth factor receptor 2 (HER2)." (PMID 33413654, 2021). "In fact, progranulin present in serum has been demonstrated to predict recurrence in hormone positive (ERα and progesterone receptor (PR) positive) breast cancer patients during tamoxifen treatment." (PMID 33618683, 2021). "The majority of respondents had low annual incomes (77.0%), had estrogen receptor or progesterone receptor positive breast cancers (97.2%), and were human epidermal growth factor receptor-2 (HER2)-negative (76.1%)." (PMID 34895183, 2021). "Around 75% of all breast cancer cases express the estrogen receptor (ER) and/or the progesterone receptor (PgR) and are considered hormone receptor-positive (HR) tumors." (PMID 33530456, 2021). "The aim of our retrospective study was to propose better prognostic cut-off levels for ER and PgR, and their effects on breast cancer-specific survival (BCSS) and disease-free survival (DFS) over 5 and 10 years were evaluated in 1807 eligible patients." (PMID 33670083, 2021). "Breast cancer can be divided into several subtypes, based primarily on the expression of estrogen receptor (ER), progesterone receptor (PR), and human epidermal growth factor receptor 2 (HER2)." (PMID 34298668, 2021). "Breast cancers that lack expression of the predictive markers oestrogen receptor, progesterone receptor and human epidermal growth factor receptor-2 are known as triple-negative breast cancers (TNBCs) and are generally considered to have a poor prognosis." (PMID 34830849, 2021). "For example, for breast cancer, we collect the status of standard biomarkers, estrogen receptor (ER), progesterone receptor (PR), human epidermal growth factor receptor 2 (HER2) receptor and BRCA mutation status, when available." (PMID 33572220, 2021). "Triple-negative breast cancer (TNBC) is a specific type of breast cancer which lacks the expression of estrogen receptor (ER), progesterone receptor (PR), and human epidermal growth factor receptor (HER2)." (PMID 34621746, 2021). "Currently, it is not fully known how WT1 interacts with tumor markers used in the characterization of breast cancer, such as the estrogen receptor, progesterone receptor, and Her2/neu." (PMID 34845427, 2021). "Most breast cancer targeting therapies aim at the three receptors: estrogen receptor (ER), progesterone receptor (PR), or epidermal growth factor receptor 2 (HER2)." (PMID 34077462, 2021). "Triple-negative breast cancer (TNBC) is an aggressive breast cancer subtype that lacks significant expression of estrogen receptor, progesterone receptor, and HER2." (PMID 34638394, 2021). "Gallen Consensus classified breast cancer into five subtypes according to the biomarker expression (estrogen receptor [ER], progesterone receptor [PR], human epidermal growth factor receptor-2 [HER2], and Ki67) evaluated using immunohistochemistry (IHC)." (PMID 34856951, 2021). "We undertook this study to determine functional ER in patients with ER+ breast cancer by using FFNP-PET to measure the change in tumor PgR levels in vivo in response to a brief dosage of estradiol." (PMID 33531464, 2021).
breast cancer (continued). "Breast cancer can be categorized into at least four subtypes based on the status of molecular markers for estrogen receptor (ER), progesterone receptor (PR), and human epidermal growth factor 2 (HER2)." (PMID 34256710, 2021). "Breast cancers have been categorized into three major subtypes based on the presence of the hormonal receptors-estrogen receptor (ER), progesterone receptor (PR), and human epidermal growth factor 2 (HER2)." (PMID 34830869, 2021). "Breast cancer is highly heterogeneous and can be identified by the expression states of estrogen receptor (ER), progesterone receptor (PR), and human epidermal growth factor receptor 2 (HER2) into four intrinsic subtypes." (PMID 34953500, 2021). "Generally, patients with estrogen receptor (ER)- or progesterone receptor (PR)-positive breast cancer are treated with adjuvant endocrine therapy for five years after surgical treatment." (PMID 34239805, 2021). "The expression of these proteins was investigated in vitro using a panel of breast cancer cell models (estrogen and progesterone receptor positive: MCF-7, MDA-MB-361; and estrogen and progesterone receptor negative: MDA-MB-231)." (PMID 34577048, 2021). "The hormone receptor-positive molecular subtype represents 64% of the diagnosed breast cancer cases and is characterized by the expression of estrogen receptor (ER) or progesterone receptor (PR) (ER and/or PR)." (PMID 34066023, 2021). "It is important to note that ER and PgR-positive IDC is the most common subtype accounting for >70% of breast cancers." (PMID 33466869, 2021). "Thyroid cancer survivors also have been found to develop breast cancer early, have more estrogen and progesterone receptor positive tumors, and have a greater incidence of mixed invasive cancer." (PMID 33451072, 2021). "In cultured breast cancer cells, estrogen and progesterone receptor antagonists inhibited the production of 4PYR metabolites." (PMID 34580423, 2021). "Breast cancer is divided different subtypes in expression of estrogen receptor (ER), progesterone receptor (PgR), and human epidermal growth factor 2 (HER2)." (PMID 34066808, 2021). "The most common subtype is the hormone receptor-positive breast cancer and approximately 70–75% of all breast cancers expressing the estrogen receptor (ER) and/or progesterone receptor (PR)." (PMID 33611659, 2021). "Such endocrine inhibitors have been the primary systemic treatment for estrogen or progesterone receptor positive breast cancer." (PMID 33796466, 2021). "First, we analyzed a larger number of patients with breast cancer expressing a low level of either ER or PgR than that assessed by previous studies." (PMID 34638491, 2021). "Breast cancer is grouped into several subtypes based on molecular characteristics including: estrogen receptor positive and progesterone receptor positive (luminal A, luminal B), HER2 overexpression (HER2+), and triple-negative breast cancer (TNBC)." (PMID 34777466, 2021). "Our retrospective study investigated the characteristics and survival of 6042 breast cancer patients according to four HR groups of combined estrogen and progesterone receptor expression." (PMID 34638491, 2021). "Tumors from 6042 patients with breast cancer were retrospectively analyzed for combined HR levels of ER and PgR." (PMID 34638491, 2021). "Triple negative breast cancer (TNBC) is a subset of breast cancer which lacks the expression of estrogen receptor (ER), progesterone receptor (PR), and human epidermal growth factor receptor-2 (HER2)." (PMID 34575658, 2021). "The lower the ER or PgR expression levels are, the closer the clinical patterns are to HR-negative breast cancer." (PMID 34638491, 2021). "Biomarkers that define breast cancer treatment recommendations include estrogen receptor (ER), progesterone receptor (PR), and human epidermal growth-factor receptor 2 (HER2); histological grade; and in many countries, the Ki67 proliferation index." (PMID 33803148, 2021).
breast cancer (continued). "Currently prediction of response to PET can only be based on the routinely measured receptors on breast cancer biopsy samples, i.e. ER, progesterone receptor (PgR) and human epidermal growth factor receptor 2 (HER2)." (PMID 33226492, 2021). "The breast cancer cell line can be classified based on the status of three important receptors, including estrogen receptor (ER), progesterone receptor (PR), and human epithelial receptor-2 (HER2)." (PMID 34677334, 2021). "Triple-negative breast cancers (TNBCs) are the breast cancers that lack expression of estrogen receptor (ER), progesterone receptor (PR) and human epidermal growth factor receptor (HER)-2/neu." (PMID 34359650, 2021). "Breast cancer is classified according to the expression of three specific molecular markers; estrogen receptor (ER), progesterone receptor (PR) and human epithelial growth factor receptor 2 (EGFR2/HER2)." (PMID 33801373, 2021). "Different types of miRNAs are related to specific subtypes of breast cancer pathological characteristics in terms of estrogen and progesterone receptor expression, tumor state, vascular invasion and proliferation information." (PMID 34743742, 2021). "Breast cancer is a common hormone-related cancer, which includes estrogen receptor-positive and progesterone receptor-positive disease." (PMID 33670046, 2021). "The MCF-7 breast cancer cell line showed that both pollutants increased the expression of ER receptor target genes, including the progesterone receptor, bcl-2, and trefoil factor." (PMID 34199666, 2021). "Until today, the immunohistochemical status of estrogen receptor alpha (ERα), progesterone receptor (PR), and human epidermal growth factor receptor-2 (HER2) has been widely used as a diagnostic tool, based on which the therapy for breast cancer is determined." (PMID 33562134, 2021). "Breast cancer stratification based on estrogen receptor (ER), progesterone receptor (PR), and human epidermal growth factor receptor 2 status have become critical factors for predicting prognosis." (PMID 34579037, 2021). "ChNPs can work by delivering anticancer drug to all widely use cancer cells that repre-sent all type breast cancer ER (estrogen receptor), PR (progesterone receptor), and Her2 (human epidermal receptor 2) and triple negative breast cancer." (PMID 34074020, 2021). "For determining molecular targeted therapy of breast cancer, for example, such markers as estrogen receptor (ER), progesterone receptor (PgR), human epidermal growth factor receptor-2 (HER2), and Ki-67 are consistently immunostained." (PMID 34203756, 2021). "First, the proportion of patients with breast cancers expressing a low level of both ER and PgR was minute compared to the total number of patients." (PMID 34638491, 2021). "Triple-negative breast cancer (TNBC) accounts for 20% of breast cancers (BCs), where the tumorigenic cells are negative for the estrogen receptor (ER), progesterone receptor (PgR), and human epidermal growth factor receptor 2 (HER2; i.e., ER–, PgR–, HER2–)." (PMID 33426510, 2021). "Over 70% of patients with breast cancer have hormone-receptor-positive disease, characterized as being estrogen-receptor-positive (ER+), progesterone-receptor-positive (PgR+), or both." (PMID 33531464, 2021). "The most significant univariate associations were the t3/t1 ratio with tumor ER status (p = 4.7 × 10−4), PgR status (p = 1.2 × 10−3) and breast cancer subtype (p = 9.8 × 10−5)." (PMID 33810361, 2021). "The assessment of estrogen and progesterone receptor expression not only is well-known management for breast cancer diagnosis but also is a predictive factor for the response of hormonal adjuvant therapy." (PMID 33517609, 2021). "Several targets belong to the estrogen receptor, such as ESR1 (estrogen receptor-α, degree = 5), ESR2 (estrogen receptor-β, degree = 5), and PGR (progesterone receptor, degree = 6), are major therapeutic targets of breast cancer." (PMID 34083561, 2021).
breast cancer (continued). "Luminal-type breast cancers are characterized by the expression of both estrogen receptor (ER) and progesterone receptor (PgR)." (PMID 33668933, 2021). "Breast cancer that lacks the expression of estrogen receptor (ER), progesterone receptor (PR), and human epidermal growth factor receptor 2 (HER2) is classified as TNBC." (PMID 33903614, 2021). "Estrogen receptor α (ERα) and progesterone receptor (PgR) are crucial prognostic and predictive biomarkers in breast cancer (BC)." (PMID 34638241, 2021). "Hormone receptor-positive HER2-negative breast cancer (HR + BC) is the most prevalent BC characterized by estrogen or progesterone receptor (ER/PR) positive HER2-negative malignant cells comprised of about 60–70% of all BC." (PMID 34064867, 2021). "Estrogen receptor α (ERα) and progesterone receptor (PgR) are crucial prognostic and predictive biomarkers that are usually co-expressed in breast cancer (BC)." (PMID 34638241, 2021). "Breast cancer can be divided into three biologic subtypes, based on biomarkers, such as the estrogen receptor (ER), progesterone receptor (PR), and human epidermal growth receptor 2 (HER2); each subtype exhibits a distinct prognostic significance." (PMID 32483122, 2020). "The androgen receptor is expressed in more than 70% of primary breast cancers; usually, its expression is correlated to ERα and PgR." (PMID 31952272, 2020). "Triple-negative breast cancer (TNBC) is a breast cancer subtype which is heterogeneous in nature and has the characteristic of negativity for estrogen receptor (ER), progesterone receptor (PR), and epidermal growth factor receptor (EGFR or HER2)." (PMID 31936263, 2020). "miRNAs were also related to certain biological features of breast cancer, like ER and progesterone receptor (PR) expression, as well as the tumor stage and invasion." (PMID 33374170, 2020). "In this review we will concentrate on the role of progestins (Pg) on the regulation of gene expression via their specific progesterone receptor (PR), focusing on breast cancer cells." (PMID 32485671, 2020). "Our recent clinical study of the changes in PgR measured by FFNP-PET in advanced breast cancer, uses the same 1-day estradiol challenge paradigm (NCT02455453)." (PMID 32718075, 2020). "A member of the nuclear receptor family, the progesterone receptor is a well-known, estrogen receptor (ER)-regulated gene that is expressed in more than two-thirds of ER-positive breast cancers." (PMID 33282730, 2020). "The expression ratios of CD155α were significantly higher in ER-negative and PgR-negative breast cancers than in ER-positive and PgR-positive breast cancers, respectively." (PMID 31372841, 2020). "Single hormone receptor-positive breast cancers are less common and their clinical course is less favorable than ER(+)/PgR(+) tumors." (PMID 32825530, 2020). "Another target gene of ERα, PgR is also involved in the acceleration of cellular proliferation via the up-regulation of cyclin D1 expression in breast cancer cells." (PMID 33177647, 2020). "Megestrol Acetate, a progesterone receptor agonist, is under various clinical trials either alone or in combination with other cancer drugs for breast cancer treatment (i.e., NCT03306472 and NCT03024580)." (PMID 32503412, 2020). "Etiologic studies generally group breast cancer into two or more protein-based subtypes using immunohistochemistry expression of estrogen receptor (ER), progesterone receptor (PR), and HER2." (PMID 31535320, 2020). "According to molecular features, breast cancers are subdivided in subtypes, according to activation of hormone receptors (estrogen receptor and progesterone receptor), of human epidermal growth factors receptor 2 (HER2), and or BRCA mutations." (PMID 32210163, 2020). "Triple-negative breast cancer, which lacks expression of estrogen receptor (ER), progesterone receptor (PR) and human epidermal growth factor receptor 2 (Her-2), is the most aggressive subtype of breast cancer and has a poor prognosis." (PMID 32332865, 2020).
breast cancer (continued). "Triple‐negative breast cancer (TNBC) is one of the most aggressive subtypes of breast cancer with negativity for oestrogen receptor (ER), progesterone receptor (PR) and human epidermal growth factor receptor (HER2)." (PMID 32249490, 2020). "ER and PgR play a major role in breast cancer cell development and positively correlated with breast cancer cell proliferation." (PMID 33112549, 2020). "Typically, breast cancer is classified into three major subtypes based on molecular markers: ER or progesterone receptor (PR)-positive (luminal A and luminal B), human epidermal growth factor receptor 2 (HER2)-positive, and TNBC." (PMID 33292526, 2020). "Triple-negative breast cancer (TNBC) is a subset of breast cancer that lacks expression of estrogen receptor (ER), progesterone receptor (PR), and human epidermal growth factor receptor 2 (HER2)." (PMID 33628740, 2020). "In patients with cT1N0M0 breast cancer, 262 patients (82.1%) were positive for ER, 194 (60.8%) were positive for PgR, and 24 (7.5%) were positive for HER2." (PMID 32590956, 2020). "Triple-negative breast cancer (TNBC) is the most aggressive type of breast cancer that lacks the oestrogen receptor, progesterone receptor and human epidermal growth factor receptor 2, making it difficult to target therapeutically." (PMID 33221821, 2020). "Breast cancer is subdivided into three types based on receptors, including progesterone receptor (PR), estrogen receptor (ER), and the human epidermal growth factor receptor 2 (HER2, also known as ErbB2)." (PMID 32746451, 2020). "We found that in the Th2 cell line (CCRF-CEM) and primary Th2 cells PGR mRNA was undetectable by qRT-PCR, though present in a breast cancer cell line (MCF-7)." (PMID 33076829, 2020). "In more recent preclinical imaging studies in mice, FFNP showed efficient and selective PgR-mediated uptake in a syngeneic mouse mammary cancer system." (PMID 32718075, 2020). "When determining the course of breast cancer treatment, it is important to evaluate the status of estrogen receptor (ER), progesterone receptor (PgR), and human epidermal growth factor receptor 2 (HER2) expression." (PMID 32248830, 2020). "A recent population study in the United States has described four molecular breast cancer subtypes based on the expression of three tumor markers, namely estrogen receptor (ER), progesterone receptor (PR), and human epidermal growth factor receptor (HER2)." (PMID 33415093, 2020). "Generally, more than 70% of women with breast cancer are ER-positive, while those PgR-positive represent 50%." (PMID 32471217, 2020). "Steroid hormone receptors, including estrogen receptor (ER) and progesterone receptor (PR), are crucial biomarkers in breast cancer (BC)." (PMID 31899528, 2020). "Triple-negative breast cancer (TNBC) accounts for approximately 15% of all breast cancers (BCs) and lacks estrogen receptor (ER) and progesterone receptor (PR) expression as well as human epidermal growth factor receptor 2 (HER2) amplification." (PMID 31937819, 2020). "This was a retrospective study enrolling a small, clinically heterogenous cohort determined by frequency of ER(−)/PgR(+) cancers in the population (~1% of all breast cancers)." (PMID 32825530, 2020). "The three clinically most-useful receptors status to characterize breast cancer cells are the estrogen receptor (ER), progesterone receptor (PR), and human epidermal growth factor receptor 2 (HER2) that can impact therapy and prognosis." (PMID 32102334, 2020). "Different subtypes of breast cancer include estrogen receptor alpha (ERα), overexpressed in approximately 70% of invasive breast cancers, and progesterone receptor (PR), overexpressed in over two-thirds of estrogen receptor positive (ER+) breast cancers." (PMID 31936496, 2020). "Tumor specimens from 36 chemonaive breast cancer patients with known ER and PgR status (18 ER(+)/PgR(−) and 18 ER(−)/PgR(+) cases) were enrolled to the study." (PMID 32825530, 2020).